CAMKK2 (calcium/calmodulin dependent protein kinase kinase 2)
Diseases named in the same sentence as CAMKK2 in open-access papers (continued):
Sharing a sentence is not in itself a finding about the gene and the disease.
ovarian carcinoma (10 papers, 2017 to 2025). A malignant neoplasm originating from the surface ovarian epithelium. "It was reported that knockdown of CAMKK2 potentiated the effect of carboplatin in ovarian cancer by modulating Akt pathway." (PMID 36606188, 2022). "Other studies reported that calcium could activate this survival pathway through a calcium/CaM/CaMKK2 complex that bound to and activated P-Akt(Thr308) in ovarian carcinoma cells." (PMID 30338034, 2018). "Indeed, CAMKK2 was shown to regulate the phosphorylation of Akt at both the threonine and serine residues in ovarian cancer cells, and combined downregulation of the CAMKK2 and PDK1 proteins had comparable effects on Akt phosphorylation, as did pharmacological inhibition of CAMKK2 and PI3K." (PMID 29064423, 2017).
glioma (9 papers, 2016 to 2024). A benign or malignant brain and spinal cord tumor that arises from glial cells (astrocytes, oligodendrocytes, ependymal cells). "To resolve whether CaMKK2 in stromal cells or the tumor itself might drive tumor progression, we sought to determine if CaMKK2 deficiency in the tumor-bearing host was sufficient to extend survival in syngeneic orthotopically implanted glioma models." (PMID 36309495, 2022). "In our study, CAMKK2 expression was significantly lower compared to normal brain in both canine and human gliomas, making it an attractive candidate gene for further investigations." (PMID 27171399, 2016). "A locus on canine chromosome (CFA) 26 has been strongly associated with glioma risk across multiple dog breeds, with regional mapping revealing single nucleotide variants in three neighboring genes DENR, CAMKK2, and P2RX7 that are highly associated with glioma susceptibility." (PMID 31788444, 2019). "Using a subset of data from the Cancer Genome Atlas (TCGA) consisting of mRNA expression data of surgical specimens from 24 glioblastoma patients, and 10 non-tumor control brains (epilepsy resections), we confirmed the lower mRNA expression of CAMKK2 in high-grade glioma." (PMID 27171399, 2016). "Because normal brain, in both dogs and humans, express higher levels of CAMKK2 than glioma, we propose that targeting CAMKK2 should involve its activation rather than inhibition." (PMID 27171399, 2016).
bipolar disorder (7 papers, 2015 to 2024). A disorder of the brain that causes unusual shifts in mood, energy, activity levels and the ability to carry out day-to-day tasks. "These dual, function-enhancing effects of lithium are noteworthy, given the connection between CaMKK2 loss-of-function and bipolar disorder." (PMID 37730845, 2023). "Loss-of-function polymorphisms and a rare missense mutation in human CAMKK2 are associated with bipolar disorder, and genetic deletion of Camkk2 in mice causes bipolar-like behaviours similar to those in patients." (PMID 37730845, 2023). "Intriguingly, the rs1063843 polymorphism that is associated with bipolar disorder and reduced CAMKK2 mRNA expression in the human brain, is also associated with functional impairment of the caudate nucleus." (PMID 37730845, 2023). "Taken together, these findings support the view that loss-of-function genetic variations in human CAMKK2 are prime candidates as potential underlying causes of bipolar disorder." (PMID 37730845, 2023). "CAMKK2 rs1063843 is associated with reduced CAMKK2 mRNA expression, consistent with the idea of reduced mitochondrial function and energy generation in bipolar depression." (PMID 37386057, 2023). "While the underlying mechanisms of memory loss and cognitive impairment in bipolar disorder remain uncertain, these data indicate that defects in CaMKK2-CaMK1 signalling may play a role." (PMID 37730845, 2023). "Also, the CAMKK2 signaling activity is required for the healthy activity of the brain which otherwise can cause diseases like bipolar disorders and anxiety." (PMID 33082841, 2020). "Increasing NRF2 activity has been proposed as a treatment approach for bipolar disorder, and activating the CaMKK2 signalling pathway represents a potential and viable mechanism to achieve this outcome." (PMID 37730845, 2023). "In relation to CaMKK2, a pharmacogenomic study using a methamphetamine-induced model of bipolar disorder in mice found that valproate treatment increased Camkk2 mRNA expression in the brain caudate nucleus." (PMID 37730845, 2023). "An ever-expanding body of scientific literature points to the CaMKK2 signalling pathway as a contributing factor in the pathogenesis of bipolar disorder." (PMID 37730845, 2023). "A future challenge is to identify highly selective and potent, small-molecule drugs capable of activating CaMKK2 in the brain, which can then be validated preclinically in human induced pluripotent stem cell (iPSC) and animal models of bipolar disorder." (PMID 37730845, 2023). "The role of the CaMKK2-Akt/PKB signalling axis in the brain has yet to be studied; however, similar to CaMKK2, there are multiple lines of evidence that demonstrate a link between loss of Akt/PKB signalling and bipolar disorder." (PMID 37730845, 2023). "Here, we review an emerging treatment target for bipolar disorder, the Ca2+-calmodulin-dependent protein kinase kinase-2 (CaMKK2)." (PMID 37730845, 2023). "In this review, we discuss multiple convergent lines of evidence that support targeting of CaMKK2 as a new treatment strategy for bipolar disorder." (PMID 37730845, 2023). "We propose CaMKK2 as a rational treatment target for bipolar disorder as it links together key facets of the condition including genetic polymorphisms/mutations, defects in signal transduction, mood stabiliser action, and metabolic dysfunction." (PMID 37730845, 2023). "Some of the aberrations in brain energy metabolism associated with bipolar disorder are similar to the metabolic phenotype displayed by cells lacking CaMKK2." (PMID 37730845, 2023). "In addition, lithium increases CaMKK2 expression in the striatum, an area of the brain that displays structural abnormalities in bipolar disorder." (PMID 37730845, 2023). "The regulation of CaMKK2 by CDK5 and GSK3 has important implications for bipolar disorder aetiology for two reasons." (PMID 37730845, 2023).
bipolar disorder (continued). "Consistent with the loss-of-function effects of genetic variations in human CAMKK2, mice lacking Camkk2 display behavioural traits similar to those frequently observed in bipolar disorder." (PMID 37730845, 2023). "The substrates that link GSK3 to bipolar disorder and lithium action are not yet clear; however, there is growing evidence that CaMKK2 could be a key effector." (PMID 37730845, 2023). "Like CaMKK2, the PKA signalling pathway is also considered to play a key role in the pathogenesis of bipolar disorder, as increased cyclic AMP levels and PKA activity have been frequently observed in post-mortem brains and peripheral cells of bipolar disorder patients." (PMID 37730845, 2023).
Hyperglycemia (7 papers, 2012 to 2025). An increased concentration of glucose in the blood. "CAMKK2 is a potent regulator of whole-body glucose metabolism, making it a promising therapeutic target for controlling hyperglycemia." (PMID 35216322, 2022). "Specifically, rFGF4 failed to reduce hyperglycemia in high fat diet fed CaMKK2-/- mice." (PMID 34907199, 2021).
schizophrenia (7 papers, 2015 to 2026). A major psychotic disorder characterized by abnormalities in the perception or expression of reality. "Elevated CaMKK2 activity is strongly associated with prostate and hepatic cancers, whereas reduced CaMKK2 activity has been linked to schizophrenia and bipolar disease in humans." (PMID 28230171, 2017). "On the other hand, behavioural disorders such as schizophrenia and bipolar disease are strongly linked to decreased CaMKK2 activity." (PMID 28230171, 2017). "Mutations that reduce expression or give rise to a Thr85Ser (T85S) mutation of Ca2+-CaM-dependent protein kinase kinase-2 (CaMKK2) have been implicated in behavioural disorders such as anxiety, bipolar and schizophrenia in humans." (PMID 26395653, 2015). "Meanwhile, there is evidence that CAMKK2 is a susceptibility gene of Schizophrenia." (PMID 34394017, 2021). "CaMKK2 has been implicated in schizophrenia, bipolar disease, neurodegeneration, and cancer." (PMID 30525042, 2018). "Enrichment of calcium-binding proteins among the top predicted targets for the phenothiazine antipsychotic thiethylperazine highlights a potential role for dysregulated calcium signaling, including calmodulin-CaMKK2 pathways, in schizophrenia pathology and treatment response." (PMID 41676525, 2026).
gastric cancer (6 papers, 2020 to 2024). A primary or metastatic malignant neoplasm involving the stomach. "Since several studies have pointed out a cross talk between STKs and TKs, we sought to study how CAMKK2 regulates tyrosine phosphorylation and the associated signaling cascades in gastric cancer." (PMID 35646067, 2022). "Our group has shown in detail the regulation of the molecular profile associated with CAMKK2 and signaling pathways regulated by CAMKK2 in gastric cancer." (PMID 35646067, 2022). "We carried out label-free quantitative tyrosine phosphoproteomics to investigate tyrosine-mediated molecular signaling associated with CAMKK2 in gastric cancer cells." (PMID 35646067, 2022). "For instance, CAMKK2, overexpressed in 94% (92 of 98) of gastric cancer cases, contains two variants that differentially modulate neuronal differentiation." (PMID 33281863, 2020). "It has been shown that CAMKK2 works in the MEK/ERK1 signaling cascade alongside CDK1 to achieve the progression of gastric cancer." (PMID 36769170, 2023). "A study of gastric cancer reported that CAMKK2 can over-activate microchromosome maintenance proteins in gastric cancer cells through MEK/ERK pathway to promote cancer cell proliferation." (PMID 37480569, 2023). "In this study, we evaluated the regulation of tyrosine phosphorylation by CAMKK2 in gastric cancer by mass spectrometry–based phosphotyrosine proteomic analysis." (PMID 35646067, 2022). "Our work provides a scaffold for future studies to investigate the role of CAMKK2 in regulating tyrosine signaling in gastric cancer." (PMID 35646067, 2022). "Our data provide a glimpse of CAMKK2-regulated tyrosine signaling in gastric cancer cells, which involves the PTK2/JUN/STAT3 axis." (PMID 35646067, 2022). "List of pathways significantly enriched from hypo‐phosphorylated proteins upon inhibition of CAMKK2 in gastric cancer cells." (PMID 35646067, 2022). "We have reported decreased phosphorylation of TYK2 at Y292, PTK2 at Y662, and STAT3 at Y705, Y737 upon inhibition of CAMKK2 in gastric cancer cells." (PMID 35646067, 2022). "Our previous studies show that inhibition of CAMKK2 decreases cellular migration of gastric cancer cells." (PMID 35646067, 2022). "Apart from the role of CAMKK2 in normal pathophysiological conditions, it is reported to be overexpressed in multiple cancers, such as gastric cancer." (PMID 35646067, 2022). "This study will serve as a road map for CAMKK2 and its downstream signaling in gastric cancer and offer a potential starting point for further mechanistic studies." (PMID 35646067, 2022). "It is the first high-throughput study to profile CAMKK2-regulated phosphotyrosine proteome in gastric cancer." (PMID 35646067, 2022). "Our data revealed decreased phosphorylation of PTK2, c-JUN, and STAT3 upon inhibition and siRNA-mediated silencing of CAMKK2 in gastric cancer cells." (PMID 35646067, 2022). "Our data show a decreased phosphorylation of EFNB2 at Y306 in gastric cancer cells upon inhibition of CAMKK2." (PMID 35646067, 2022). "Our results revealed a significant decrease in cellular proliferation upon inhibiting or silencing CAMKK2 in gastric cancer cells." (PMID 35646067, 2022). "Our data revealed a significant decrease in phosphorylation of PRKCD at Y334 upon inhibition of CAMKK2 in gastric cancer cells." (PMID 35646067, 2022). "Our previous studies have reported that CAMKK2 regulates multiple pathways involved in cellular transformation in gastric cancer cells and activates CDK by CAMKK2 through the MEK-ERK pathway, promoting cellular proliferation in gastric cancer cells." (PMID 35646067, 2022). "CAMKK2 is reported to be overexpressed in gastric cancer; however, its signaling mechanism is poorly understood." (PMID 35646067, 2022). "We aimed to study tyrosine kinase signaling cascade in gastric cancer by CAMKK2 by analyzing the phosphotyrosine protein profiling in gastric cancer cells via inhibition of CAMKK2." (PMID 35646067, 2022).
gastric cancer (continued). "Our results showed that CAMKK2 inhibition decreases the tumorigenesis in gastric cancer cells by reducing the phosphorylation of kinases involved in GC tumorigenesis." (PMID 35646067, 2022). "Our data show a decrease in the phosphorylation of TYK2 at Y292 and STAT3 at Y705 and Y737 on inhibition of CAMKK2 in gastric cancer." (PMID 35646067, 2022). "Our western blot data revealed decreased phosphorylation of PTK2 at Y925, p-c-JUN at S73, STAT3 at Y705, and AMPK at T172 upon both inhibition and silencing of CAMKK2 in gastric cancer." (PMID 35646067, 2022). "The study indicates that inhibition of CAMKK2 has an anti-oncogenic effect in gastric cells regulating phosphorylation of STAT3 through PTK2/c-JUN in gastric cancer." (PMID 35646067, 2022). "Our group has reported overexpression of CAMKK2 in gastric cancer." (PMID 35646067, 2022). "Our group has recently reported regulation of the MEK-ERK pathway by CAMKK2 in gastric cancer." (PMID 35646067, 2022). "This indicates that CAMKK2-mediated signaling may orchestrate through PTK2/JUN/STAT3 signaling in gastric cancer." (PMID 35646067, 2022). "Interestingly, we have found decreased phosphorylation of ANXA2 at Y715 and a decrease in phosphorylation of STAT3 upon inhibition of CAMKK2 in gastric cancer cells." (PMID 35646067, 2022). "We carried out a label-free quantitative phosphotyrosine proteomic analysis to investigate the role of phosphotyrosine signaling in CAMKK2-mediated progression of GC in gastric cancer (AGS) cells." (PMID 35646067, 2022). "Calcium/calmodulin-dependent protein kinase 2 (CAMKK2) works as an upstream factor for CDK1, CDK2, and ERK1 in gastric cancer, as evidenced by bioinformatics analysis." (PMID 36769170, 2023). "CAMKK2 belongs to the STK family and is reported to be overexpressed in different types of cancers, such as gastric cancer." (PMID 35646067, 2022). "To study the role of CAMKK2 in phosphotyrosine signaling, we used STO-609–mediated inhibition of CAMKK2 in gastric cancer cells." (PMID 35646067, 2022). "Our phosphoproteomic data and bioinformatics analyses lead to the identification of both kinases and non-kinases regulated by CAMKK2, which can serve as potential therapeutic targets for gastric cancer." (PMID 35646067, 2022). "List of significantly altered tyrosine‐phosphorylation of kinases upon inhibition of CAMKK2 in gastric cancer, which were not reported earlier to be regulated by CAMKK2." (PMID 35646067, 2022). "A more detailed understanding about the role of CAMKK2 in activation of the tyrosine phosphoproteome and, in particular, PTK2/JUN/STAT3 signaling in gastric cancer is needed, in addition to functional studies in preclinical models, which is beyond the scope of this article." (PMID 35646067, 2022). "In addition to kinases, we also identified decreased phosphorylation of non-kinase proteins upon inhibition of CAMKK2 in gastric cancer." (PMID 35646067, 2022). "In addition to kinases, we also observed a decrease in the phosphorylation of several non-kinase proteins at tyrosine residue upon inhibition of CAMKK2 in gastric cancer." (PMID 35646067, 2022).
glioblastoma (6 papers, 2016 to 2023). The most malignant astrocytic tumor (WHO grade IV). "Because CAMKK2 expression is associated with a mature cellular phenotype we next treated two of the glioblastoma cell lines with 5% serum for seven days to induce their differentiation." (PMID 27171399, 2016). "Here the authors show that Calmodulin-Dependent Kinase Kinase 2 (CaMKK2) is expressed in tumor associated macrophages and neurons and is associated with resistance to ICB in preclinical models of glioblastoma." (PMID 36309495, 2022). "Alternative splicing of the CAMKK2 exon 14 and/or 16 in human glioblastoma/astrocytoma cells and exon 16 in rat neuroblastoma cells has been reported." (PMID 32460794, 2020). "Since we found that differentiation of glioblastoma stem cells was correlated with a higher expression of CAMKK2 we suggest that CAMKK2 down regulation may render tumor cells more stem cell-like thereby increasing the aggressiveness of the tumor." (PMID 27171399, 2016). "Furthermore, we analyzed the levels of CAMKK2 expression in seven human glioblastoma patient-derived cell lines, maintained in neural stem cell medium under serum-free conditions and found that all tumors showed 20–60% lower level of expression of CAMKK2 protein compared to normal frontal cortex." (PMID 27171399, 2016).
Alzheimer disease (5 papers, 2014 to 2026). A progressive, neurodegenerative disease characterized by loss of function and death of nerve cells in several areas of the brain leading to loss of cognitive function such as memory and language. "CaMKK2 exacerbates amyloid-b synaptotoxicity in Alzheimer’s disease through Tau protein phosphorylation by AMPK20." (PMID 35927430, 2022). "An emerging body of data suggest that aberrant activation of the CaMKK2-AMPK pathway may be involved in the pathogenesis of neurodegenerative diseases such as Alzheimer’s disease, the most common form of dementia." (PMID 39268917, 2024). "Significantly, these Aβ42-induced impairments in mitochondrial function were completely blocked by pharmacological inhibition of CaMKK2, which suggests that CaMKK2 inhibition may have therapeutic potential for treating Alzheimer’s disease." (PMID 39268917, 2024).
Cerebral ischemia (5 papers, 2014 to 2024). Restriction of arterial blood supply to the brain associated with insufficient oxygenation to support the metabolic requirements of the tissue. "MiR-378a-5p has been found to reduce neuronal apoptosis by downregulating the expression of CAMKK2, thereby mitigating cerebral ischemia‒reperfusion injury." (PMID 39176087, 2024). "However, at present, there are limited studies on the role of miR-378a-5p in cerebral ischemia, miR-378a-5p has been found to reduce neuronal apoptosis by downregulating the expression of CAMKK2, thereby mitigating cerebral ischemia‒reperfusion injury." (PMID 39176087, 2024). "Conversely, overexpression of CaMKK2 reduced brain injury in cerebral ischemia aged mice." (PMID 37660166, 2023).
endothelial dysfunction (5 papers, 2019 to 2022). In vascular diseases, endothelial dysfunction is a systemic pathological state of the endothelium (the inner lining of blood vessels) and can be broadly defined as an imbalance between vasodilating and vasoconstricting substances produced by (or acting on) the endothelium. "FGF21-induced activation of the CaMKK2-AMPKα signaling pathway suppresses oxidative stress and enhances endothelium-dependent vasorelaxation of the aorta, thus alleviating endothelial dysfunction." (PMID 36213282, 2022). "In diabetic mice, FGF-21 ameliorates endothelial dysfunction by suppressing oxidative stress and enhancing endothelium-dependent vasorelaxation through the activation of calcium/calmodulin-dependent protein kinase kinase 2 (CaMKK2)/protein kinase AMP-activated catalytic subunit alpha (AMPKα)." (PMID 33081064, 2020). "Therefore, FGF21 induces relaxation of aorta through CaMKK2/AMPKα activation may also contribute to the alleviation of endothelial dysfunction in addition to its potent inhibition on oxidative stress." (PMID 31511499, 2019).